CD4 (CD4 molecule)
Diseases named in the same sentence as CD4 in open-access papers (continued):
Sharing a sentence is not in itself a finding about the gene and the disease.
influenza (continued). "Next, we analyzed the cellular responses in mice treated with influenza and found that there was a higher frequency of CD45+ CD11b+ Ly6G+ neutrophils and CD45+ CD4+ T cells present in the hearts of influenza-infected mice when compared to the PBS controls." (PMID 38750107, 2024). "A study conducted in 2014 showed that consumption of Everolimus in healthy elderly improved protective response after an influenza vaccination as a consequence of expression reduction in programmed cell death-1 receptor on CD8 + and CD4 + T-cells." (PMID 38745015, 2024). "CD4+ and CD8+ T cells have an important role to play in the protective immune response to an influenza infection." (PMID 39221016, 2024). "We next analyzed I-Ab:gp66-77 tetramer+ CD4+ T cells for CXCR5, PD-1, and BCL6 expression following influenza infection in medLN to determine the kinetics of memory antigen-specific Tfh cells." (PMID 39283916, 2024). "One study revealed a decrease in CD4+ T lymphocytes and a decrease in CD4+/CD8+ in patients with severe influenza pneumonia." (PMID 39624480, 2024). "Contrary to influenza-specific cells, the expression of HLA-DR and CD38 in memory cit-TNC CD4+T cells was confined to only a few individuals, while being commonly expressed in the former cell population." (PMID 39557489, 2024). "Overall, frequencies of total CD4, CD8 and ɣδ T cells were similar between males and females in response to LAIV and to other influenza antigens." (PMID 38812520, 2024). "In brief, memory CD4+ T cells from two patients (PT2 and PT16) were stimulated in vitro with either PNS-myelin or influenza antigens." (PMID 38233524, 2024). "The protective role of CD4+ and CD8+ T-cell responses in humans has been demonstrated in experimental influenza challenge studies." (PMID 39397062, 2024). "Our results demonstrate that CD4+/CD25+FoxP3+ Tregs are involved in the pathogenesis of severe influenza and indicate the potential of the MEK-inhibitor zapnometinib to modulate CD4+/CD25+FoxP3+ Tregs." (PMID 38979428, 2024). "In influenza immunogenicity, T cells are very important, as CD4+ and CD8+ T cells respond to conserved viral proteins, allowing them to recognize and react to multiple influenza strains." (PMID 39772053, 2024). "We found that CyCMV/Flu vectors induced influenza-specific CD8+ and CD4 + TEM, with the influenza-specific CD8 + T cells being restricted by MHC-Ia in FL CyCMV/Flu-vaccinated MCM and MHC-II or MHC-E in dd CyCMV/Flu-vaccinated MCM." (PMID 39030218, 2024). "As expected with CMV-based vectors, CyCMV/Flu-elicited CD4+ and CD8 + T cells recognizing influenza antigens exhibited a predominantly TEM phenotype in peripheral blood as measured by expression of CD28 and CCR7." (PMID 39030218, 2024). "In summary, influenza vaccine responses in HIV-infected individuals are influenced by various factors (age, CD4+ cell counts, preexisting antibodies, and inflammatory monocytes), and adjuvanted vaccines demonstrate improved immunogenicity." (PMID 38792562, 2024). "Consistently, CD4+ T cell-dependent immunity, such as EAE and antiviral immunity to influenza, was compromised." (PMID 37925509, 2023). "Overall, dynamics of the three cTFH cell subpopulations (cTFH1 [CD3+CD4+CXCR5+CXCR3+CCR6−], cTFH2 [CD3+CD4+CXCR5+CXCR3−CCR6−], and cTFH17 [CD3+CD4+CXCR5+CXCR3−CCR6+]) differed after influenza vaccination." (PMID 36705404, 2023). "The CD4+ T cell activating CPI (a mixture of protein antigens from cytomegalo-, influenza and parainfluenza viruses) was used as an alternative antigen to TT." (PMID 38124752, 2023). "The numbers of activated CD8 T cells, effector memory CD4 T cells, memory B cells, and central memory CD8 T cells were significantly reduced in influenza and COVID patients." (PMID 36911695, 2023). "In severe tuberculosis and influenza, for example, sensing eATP via P2RX7-expressing CD4+ T cells increases disease severity." (PMID 37143525, 2023).
influenza (continued). "This influenza VLP vaccine produced a robust immune response after just one injection, generating strong antigen-specific CD4+ T cells and antibody responses in response to the plant-based VLP influenza vaccination." (PMID 38030859, 2023). "There was a weak but significant positive correlation between CD4 responses to SARS-CoV-2 spike and CD4 responses to influenza peptides in rituximab-treated patients, suggesting individual differences to vaccine antigens in general." (PMID 37159281, 2023). "In this analysis, we found that the numbers of activated CD8 T cells, effector memory CD4 T cells, memory B cells, and central memory CD8 T cells were significantly reduced in influenza and COVID patients." (PMID 36911695, 2023). "After influenza infection, CD4+ TRM cells isolated from the lungs of mice have been shown to mediate enhanced viral clearance and survival during fatal influenza infections." (PMID 36032142, 2022). "Similar to the case in primary infection, lung tissue resident T cells, including Treg, CD4+Foxp3-, and CD8+ T cell subsets all expanded following secondary influenza infection." (PMID 36159872, 2022). "Furthermore, the requirement for CD4 T cell epitopes to facilitate CD8 T cell killing in addition to humoral responses means that the direct observation of HLA-II peptides will be extremely valuable in improving vaccines for combating potential influenza outbreaks in the future." (PMID 35051231, 2022). "Enhanced responses of CD4+ T cells against CMV and influenza HA peptide pools were observed 1 month after SARS-CoV-2 mRNA vaccination." (PMID 35418996, 2022). "Both CD4+ and CD8+ T-cells induced during several influenza seasons also offer cross-protection against newly emerging pandemic strains as demonstrated during the 2009 pH1N1 pandemic." (PMID 36052083, 2022). "Mice selectively depleted of cDC ICAM-1 expression supported, however, normal CTL and Tfh differentiation following influenza infection, ruling out essential co-stimulatory functions of DC ICAM-1 in CD8+ and CD4+ T cell differentiation." (PMID 36895258, 2022). "Virus-specific CD4+ and CD8+ T cells specific for immunodominant influenza epitopes negatively correlate with disease severity and fever symptoms, respectively." (PMID 35051231, 2022). "We found CD4 and CD8 T cell response for pre-pandemic sH1N1 was associated with protection against pH1N1 infection, suggesting that subtype- or HA group-specific vaccine with a wider breadth of protection could be a promising first step toward universal influenza vaccine." (PMID 35858844, 2022). "Influenza vaccines that contain MF59 adjuvant showed better persistence of B cell and CD4+ T cell responses, and similar effects have been described for AS03." (PMID 36077216, 2022). "Reduced numbers of both CD4+ and CD8+ influenza-specific pulmonary T cells were reported during influenza infection in aged rhesus macaques and mice." (PMID 36233146, 2022). "Since monocytes can initiate adaptive immune responses, specifically CD4+ T cells, we next examined if the administration of ONP-302 impacted the number of T cells and B cells in the BAL after influenza infection." (PMID 35737459, 2022). "The ELISpot assay specifically aims at quantifying IFN-γ producing cells, such as CD4+ Th1 and CD8+ T cells which are the prime subsets of interest when examining influenza-specific responses induced by vaccination and/or infection." (PMID 36159843, 2022). "Previous studies on mice have revealed that lung CD4+ and CD8+ T cells increase along with cytokine production after influenza restimulation or vaccine administration." (PMID 36211412, 2022). "Both CD4+ and CD8+ Trm cells develop following acute influenza infection and protect against heterotypic challenge." (PMID 36159872, 2022). "CD4+ T cells reactive to CMV, influenza HA, and SARS-CoV-2 “M” and “N” were increased at 1 month post-immunization." (PMID 35418996, 2022).
influenza (continued). "This contrasts with typical findings during viral respiratory infection, such as influenza or SARS, or sepsis where lymphocytopenia is evident but CD4+/CD8+ ratios are decreased." (PMID 34226537, 2021). "Following vaccination, both CD4 and CD8 responses against the various influenza antigens were increased in day 15 to day 91 post vaccination period, and maintained a Th1 polarized profile." (PMID 33922875, 2021). "In human influenza infection, CD8+ TRM have been shown to recognise the internal, conserved proteins of the virus whereas CD4+ TRM recognise both internal and external proteins, with both cell types contributing towards heterosubtypic protection." (PMID 34603321, 2021). "CD4 T cell reactivity was mostly directed to HA/NA proteins in influenza B strains, and NP/M1/M2/NS1/NEP proteins in the case of the Influenza A strains." (PMID 33922875, 2021). "Robust CD4+ and CD8+ T-cell responses to influenza infections can protect patients from severe disease, but these responses must be induced in a carefully balanced way to prevent excessive proinflammatory reactions and increased immunopathology." (PMID 34207924, 2021). "Our results demonstrated that LAIV induced influenza-specific cytokine-producing CD8+ and CD4+ T cells, including TRM T cells in the lung." (PMID 33497364, 2021). "In an intranasal model of immunization of influenza in mice, addition of CpG significantly enhanced recruitment of CD4+ T cells in the lung producing IFN-γ, TNF-α, or multifunctional CD4+ T cells producing both cytokines." (PMID 34451945, 2021). "The results showed that CD4+ T and CD8+ T cells significantly decreased in severe influenza patients, but neutrophils increased with disease severity." (PMID 33448094, 2021). "The CXCR3-CXCL10 axis appears critical for the recruitment of CD4+ and CD8+T cells that control influenza and tuberculosis infection in the lung, respectively." (PMID 34021148, 2021). "KEGG enrichment of differentially expressed genes in activated CD4+ T cells and activated CD8+ T cells identified three (ribosome, influenza A, and NOD-like receptor signaling) and 32 pathways, respectively (adjusted p-value < 0.05)." (PMID 34484194, 2021). "Similar to influenza, CD8+ TRM recognise internal proteins of RSV, whilst CD4+ TRM recognise external proteins." (PMID 34603321, 2021). "Our study utilized a whole live virus assay to measure the kinetics of influenza-specific responses in NK cells, γδ T cells and CD161+TRAV1-2+ MAIT cells (innate-like), and CD8+ and CD4+ T cells (adaptive)." (PMID 33976217, 2021). "Complete absence of CCR5 in mice revealed the receptor’s role in coping with influenza via the recruitment of early memory CD8+ T cells, B cell activation and later recruitment of activated CD4+ T cells." (PMID 35126379, 2021). "We validated our technology by reproducing known experimental results, including differentiation patterns of CD4+ T cells triggered by different combinations of cytokines, metabolic regulation by IL2 in these cells, and their response to influenza infection." (PMID 34343169, 2021). "Lung tissue-resident memory (TRM) CD4+ and CD8+ T-cells generated following influenza infection have been shown to provoke viral clearance and survival after lethal challenge." (PMID 34177921, 2021). "Pathology is attenuated by depletion of both CD4+ and CD8+, although a delay in influenza clearance ensues." (PMID 33562512, 2021). "Inducible deletion of Bcl6 among CD4 T cells resulted in less co-localization of CD4 T cells and B cells within BALT and an overall decreased influenza-specific ASC recall response in the lung." (PMID 34970279, 2021). "Antibody responses to influenza are observed to be relatively poor in HIV-positive patients, likely due to the presence of low numbers of CD4+ T-cells and viremia." (PMID 34372607, 2021).
influenza (continued). "Akin with that, mice lacking the CCL5 scavenger Atypical Chemokine Receptor 2 (ACKR2) present increased CCL5 levels, CCR5+CD4+ lymphocyte recruitment to the airways and augmented levels of IgA in the BALF during influenza." (PMID 35126379, 2021). "Interestingly, type-specific immunodominance patterns of CD4 T cell responses remained unchanged after vaccination, and the vaccine-specific CD4 T cells targeted predominantly the “other” MP of the two influenza A strains, and the HA/NA MP of the two influenza B strains." (PMID 33922875, 2021). "NOD/Shi-scid IL2rγnull mice, retaining human CD14+ cells, plasmacytoid dendritic cells, CD4+ and CD8+ T cells, and B cells in the lungs were also demonstrated to be suitable for evaluating the safety of influenza vaccines." (PMID 34071367, 2021). "Influenza infection stimulates both naïve and memory B cells and CD4 and CD8 T cells, and is required to establish influenza-specific CD8 T cell immunologic memory." (PMID 32399058, 2020). "Influenza-specific interferon-secreting T cells, CD4+ T cells, and CD8+ T cells play an important role in recovery from influenza in humans." (PMID 32640619, 2020). "Both CD4+ and CD8+ T cells play an important role in the clearance of respiratory viral pathogens, including influenza." (PMID 33373420, 2020). "A study of influenza infection in mice demonstrated influenza-specific lung-resident memory T cells were CD69+, with CD4+ TRM cells co-expressing CD11a and CD8+ TRM cells co-expressing CD103." (PMID 32974217, 2020). "Meanwhile, the memory CD4+ and CD8+ T cell-mediated immunity initiated by influenza vaccination can only be sustained at a relatively high level of up to 6 months and followed by a sharp decline within 12 months." (PMID 32788837, 2020). "Upon infection, influenza virus activates innate immune components, leading eventually to the generation of influenza-specific CD8+ and CD4+ T-cell responses, both of which are important in controlling influenza infection." (PMID 32572168, 2020). "Infection-elicited influenza-specific CD4+ and CD8+ T-cell responses were measured using flow cytometry and intracellular cytokine staining and compared to responses following influenza vaccine in SOT patients." (PMID 32572168, 2020). "Taken together, these data suggested that FTY720 treatment compromised memory CD4 and CD8 T-cell-mediated influenza viral control in vaccinated mice." (PMID 33767689, 2020). "Protective cytotoxic CD4+ T cells have been described in response to a range of viral infections including HIV, Influenza and HCMV." (PMID 33374787, 2020). "While CD4+ and CD8+ T cells have previously been examined in influenza-infected ferrets, little work has been conducted for innate cell subsets." (PMID 33072098, 2020). "Since CD4+ T cells orchestrate anti-influenza viral immune responses including the CTL response and antibody generation, understanding CD4+ T cell mechanisms is critical for developing novel influenza vaccines." (PMID 33353154, 2020). "The protection was conferred by CD4+ and CD8+ T memory cells, which were transferred from animals previously infected with influenza or immunized with cross-reactive influenza peptides to sensitized mice before challenge with an allergen." (PMID 32296430, 2020). "In addition, to facilitate statistical comparison between the groups, influenza-specific CD4 T cells elaborating each cytokine combination were summed across stimulation conditions and presented as a ratio of cells producing each cytokine combination compared to the total CD4 T cell frequency." (PMID 30692574, 2019). "The influenza antigens NP, PB1, and M1 have been selected as they have the largest amount of conserved regions, which also included a number of recognized CD8 and CD4 T cell epitopes." (PMID 31683888, 2019).
influenza (continued). "We observed that different types of influenza vaccines (whole inactivated virus (WIV), split, and peptide vaccines) were all able to stimulate CD4 and CD8 T cell responses but to different extents in line with their reported in vivo properties." (PMID 31766202, 2019). "Expression of the CD69 activation marker was evaluated on CD4+ and CD8+ cells following incubation with the influenza vaccine antigens to demonstrate immunological sensitization previously acquired in vivo by the tested individual through vaccination." (PMID 31600331, 2019). "The intestinal microbiota composition was shown to be altered in mice with influenza infection, which was mediated by IFN-γ produced by lung-derived CCR9+CD4+ T cells recruited into the small intestine." (PMID 31750262, 2019). "Age-related homeostatic dysregulation involving the proliferation of CD4 and CD8 T-cell subsets, including Tregs, was related to a limited responsiveness to influenza vaccination and a higher inflammatory status in a cohort of elderly people." (PMID 31312227, 2019). "The data support the use of QIV for immunisation of PLWH, reveal distinct circulating CD4+CXCR5+ T cell subsets and demonstrate oral fluid sampling for influenza-specific IgG is an alternative to phlebotomy." (PMID 31666568, 2019). "Strikingly in the murine model of influenza infection, CD8+ T cells are the largest subset of the IL-10-producing LAG3+CD49b+ T cells in the lungs (86%), followed by Foxp3− CD4+ T cells, while Foxp3+ CD4+ are a minority." (PMID 30510554, 2018). "The CD4+ T lymphocytes and CD8+ T cytotoxic lymphocytes (CTLs) mediate the cellular arm of the adaptive immune response against influenza and play an important role in viral clearance and cross-protective immunity." (PMID 29467737, 2018). "For detection of CD4+ and CD8+ T cells responding to any influenza protein, splenocytes from sequentially infected or sequentially immunized mice were stimulated overnight with WIV, and IFNγ production was assessed by intracellular cytokine staining." (PMID 30356772, 2018). "Specifically, resting memory influenza specific CD4+ T cells are CD38-, but become CD38 bright in the periphery starting 7–14 days after influenza vaccination or infection." (PMID 30619245, 2018). "A Malawian study demonstrated poor reconstitution of influenza-specific CD4+ T-cell response in HIV-infected adults after 12 months of highly active ART, despite a rise in CD4+ cell count." (PMID 29045699, 2018). "Following secondary encounter with influenza virus, both CD4+ and CD8+ lung Trm rapidly acquire effector function and respond swiftly, mediating enhanced viral clearance and survival to lethal influenza infection." (PMID 29587436, 2018). "In humans, both CD4+ and CD8+ influenza specific T cells have been shown to correlate with reduced disease severity in experimental challenge and natural infection." (PMID 29552008, 2018). "CD4 and CD8 T cells from splenocytes taken early (14d) after infection showed extensive cross-reactivity between influenza subtypes and even types." (PMID 29666412, 2018). "We measured CD4+ and CD8+ T-cell reactivity in human subjects following vaccination with licensed trivalent influenza vaccine and a novel virus-like particle based vaccine." (PMID 30573748, 2018). "The current studies provide robust evidence to support these findings having prospectively ascertained HIV status, CD4+ cell count, and information on ART, as well as other exposures, including household and socioeconomic characteristics that may confound the association between HIV and influenza." (PMID 29045699, 2018). "It is widely reported that CD4+ T cells, though dispensable for primary CTL response, are central to achieve robust memory CD8+ T cell response in influenza infection." (PMID 30622538, 2018).